APPL2 (adaptor protein, phosphotyrosine interacting with PH domain and leucine zipper 2)
Description:
Multifunctional adapter protein that binds to various membrane receptors, nuclear factors and signaling proteins to regulate many processes, such as cell proliferation, immune response, endosomal trafficking and cell metabolism. Regulates signaling pathway leading to cell proliferation through interaction with RAB5A and subunits of the NuRD/MeCP1 complex. Plays a role in immune response by modulating phagocytosis, inflammatory and innate immune responses. In macrophages, enhances Fc-gamma receptor-mediated phagocytosis through interaction with RAB31 leading to activation of PI3K/Akt signaling. In response to LPS, modulates inflammatory responses by playing a key role on the regulation of TLR4 signaling and in the nuclear translocation of RELA/NF-kappa-B p65 and the secretion of pro- and anti-inflammatory cytokines. Also functions as a negative regulator of innate immune response via inhibition of AKT1 signaling pathway by forming a complex with APPL1 and PIK3R1 (By similarity). Plays a role in endosomal trafficking of TGFBR1 from the endosomes to the nucleus. Plays a role in cell metabolism by regulating adiponecting and insulin signaling pathways and adaptative thermogenesis (By similarity). In muscle, negatively regulates adiponectin-simulated glucose uptake and fatty acid oxidation by inhibiting adiponectin signaling pathway through APPL1 sequestration thereby antagonizing APPL1 action (By similarity). In muscles, negatively regulates insulin-induced plasma membrane recruitment of GLUT4 and glucose uptake through interaction with TBC1D1. Plays a role in cold and diet-induced adaptive thermogenesis by activating ventromedial hypothalamus (VMH) neurons throught AMPK inhibition which enhances sympathetic outflow to subcutaneous white adipose tissue (sWAT), sWAT beiging and cold tolerance (By similarity). Also plays a role in other signaling pathways namely Wnt/beta-catenin, HGF and glucocorticoid receptor signaling (By similarity). Positive regulator of beta-catenin/TCF-dependent transcription through direct interaction with RUVBL2/reptin resulting in the relief of RUVBL2-mediated repression of beta-catenin/TCF target genes by modulating the interactions within the beta-catenin-reptin-HDAC complex. May affect adult neurogenesis in hippocampus and olfactory system via regulating the sensitivity of glucocorticoid receptor. Required for fibroblast migration through HGF cell signaling (By similarity).
Synonyms: DIP13B; FLJ10659
Tractability: Antibody: UniProt places it where antibodies can reach, with high confidence; its Gene Ontology location is reachable by antibodies, with high confidence. PROTAC: ubiquitination databases record sites on it; its protein half-life has been measured.
Gene: Protein-coding gene on chromosome 12 (105,172,485 to 105,236,221, reverse strand). Ensembl gene ENSG00000136044.
Subcellular location: Early endosome membrane; Nucleus; Cell membrane; Endosome membrane; Cytoplasm; Cytoplasmic vesicle, phagosome; Cell projection, ruffle; Cell projection, ruffle membrane; Cytoplasmic vesicle, phagosome membrane
Subcellular location (Human Protein Atlas): Vesicles; Cytosol
Gene Ontology:
Molecular function: identical protein binding; phosphatidylinositol binding; phosphatidylserine binding; protein binding; protein homodimerization activity; protein-containing complex binding
Biological process: glucose homeostasis; negative regulation of D-glucose import; protein homotetramerization; protein import into nucleus; regulation of G1/S transition of mitotic cell cycle; transforming growth factor beta receptor signaling pathway; adiponectin-activated signaling pathway; cellular response to hepatocyte growth factor stimulus; cold acclimation; diet induced thermogenesis; negative regulation of cellular response to insulin stimulus; negative regulation of cytokine production involved in inflammatory response; negative regulation of fatty acid oxidation; negative regulation of neural precursor cell proliferation; negative regulation of neurogenesis; positive regulation of cold-induced thermogenesis; positive regulation of Fc-gamma receptor signaling pathway involved in phagocytosis; positive regulation of macropinocytosis; positive regulation of phagocytosis, engulfment; regulation of fibroblast migration; regulation of innate immune response; regulation of toll-like receptor 4 signaling pathway; signal transduction; signaling; homeostatic process
Cellular component: cytoplasmic vesicle; early endosome membrane; endosome; endosome membrane; extracellular exosome; membrane; nucleus; plasma membrane; vesicle; cytoplasm; early phagosome; early phagosome membrane; macropinosome; ruffle; ruffle membrane; bounding membrane of organelle; cytoplasmic vesicle membrane; phagocytic vesicle; phagocytic vesicle membrane
Genetic constraint (gnomAD): Loss-of-function variants: 77 observed, 86.59 expected, observed/expected ratio (o/e) 0.89, 90% interval 0.74 to 1.08. The upper end of that interval is the gene's LOEUF score, 1.08, which puts it in group 4 of 6, group 1 being the genes least tolerant of losing a copy. Missense variants: 660 observed, 769.38 expected, observed/expected ratio (o/e) 0.86, 90% interval 0.8 to 0.92. Synonymous variants: 262 observed, 273.26 expected, observed/expected ratio (o/e) 0.96, 90% interval 0.87 to 1.06.
Homologues: Orthologues: chimpanzee APPL2 (99% identical), macaque APPL2 (98% identical), dog APPL2 (94% identical), pig APPL2 (94% identical), mouse Appl2 (92% identical), rabbit APPL2 (92% identical), rat Appl2 (92% identical), guinea pig APPL2 (86% identical), tropical clawed frog appl2 (73% identical), zebrafish APPL2 (69% identical). Paralogues in human: APPL1 (54% identical), GIT1 (19% identical), GIT2 (17% identical), ARAP3 (12% identical), ARAP1 (11% identical), ASAP1 (11% identical), ASAP2 (11% identical), ARAP2 (10% identical), ASAP3 (9% identical), ACAP3 (8% identical), AGAP2 (8% identical), ACAP2 (8% identical), and 16 more.